CNNM4 (cyclin and CBS domain divalent metal cation transport mediator 4)
Diseases named in the same sentence as CNNM4 in open-access papers:
CNNM4 is named in the same sentence as 35 diseases in open-access papers, as found by Europe PMC text mining. Sharing a sentence is not in itself a finding about the gene and the disease. The quoted sentences say what the papers report.
Jalili syndrome (14 papers, 2009 to 2025). "Mutations in CNNM4 can cause Jalili Syndrome, a rare autosomal recessive condition characterized by cone–rod dystrophy of the retina and amelogenesis imperfecta." (PMID 40003994, 2025). "CNNM4 loss in Jalili syndrome produces Mg-rich, hypomineralized enamel, and Cnnm4-deficient mice confirm a basolateral Mg2+ efflux role for CNNM4." (PMID 41294875, 2025). "In humans, point mutations in CNNM2 cause hypomagnesemia, while mutations in CNNM4 are associated with Jalili syndrome." (PMID 34766907, 2021). "CNNM4 is abundant in the brain and the intestinal tract, and its abnormal activity causes Jalili Syndrome." (PMID 31842432, 2019). "cnnm-3/ CNNM4 is a metal ion transporter, and mutations in CNNM4 cause Jalili syndrome, a disorder that includes retinal cone-rod dystrophy and amelogenesis imperfecta." (PMID 31834878, 2019). "For example, mutations in CNNM2 or CNNM4 cause recessively inherited dominant hypomagnesemia and renal Mg2+ wasting or Jalili Syndrome, respectively." (PMID 31842432, 2019). "One of the common features of Jalili syndrome, which is caused by mutations in CNNM4, is AI, the malformation of tooth enamel." (PMID 24339795, 2013). "The identification of CNNM4 as the causative gene for Jalili syndrome, characterized by syndromic CRD with AI, has the potential to provide new insights into the roles of metal transport in visual function and biomineralization." (PMID 19200525, 2009). "Loss of CNNM4 function causes Jalili syndrome and produces hypomineralized, magnesium-enriched enamel, which directly implicates tight magnesium export in normal mineral development and shows the pathological consequence of intracellular magnesium retention during amelogenesis." (PMID 41294875, 2025). "To date, 20 mutations have been reported in CNNM4, in association with Jalili syndrome." (PMID 29421294, 2018). "Furthermore, CNNM4 mutations cause Jalili syndrome, characterized by recessive amelogenesis imperfecta with cone-rod dystrophy." (PMID 24339795, 2013). "CNNM4 is mutated in Jalili syndrome, which is characterized by recessive AI and CRD." (PMID 24339795, 2013). "Furthermore, we also show that these CNNM4-lacking mice also have a defect in amelogenesis, which is consistent with the disease symptoms of Jalili syndrome that is known to be caused by mutations in the CNNM4 gene." (PMID 24339795, 2013). "Jalili syndrome denotes a recessively inherited combination of an eye disease (cone-rod dystrophy) and a dental disorder (amelogenesis imperfecta), which is caused by mutations in the CNNM4 gene." (PMID 24194943, 2013). "Moreover, it has been reported that mutations in CNNM4 cause Jalili syndrome, which is characterized by recessive amelogenesis imperfecta (AI) and cone-rod dystrophy (CRD)." (PMID 24339795, 2013). "To ascertain the functional importance of Mg2+ extrusion by CNNM4, we examined whether missense point mutations in CNNM4, which have been reported to occur in the patients of Jalili syndrome, have any effects on Mg2+ extrusion activity." (PMID 24339795, 2013). "Concluding that Jalili syndrome was likely to be caused by mutations in a single gene, we sequenced 11 candidate genes in the 2q11 region and identified deleterious mutations in the CNNM4 gene (MIM ∗607805)." (PMID 19200525, 2009). "MC was recorded as appearing in CLDN-19-gene-related FHHNC and CNNM4-gene-related Jalili syndrome (JS)." (PMID 36429029, 2022).
cone-rod dystrophy (9 papers, 2013 to 2025). Inherited retinal dystrophies that belong to the group of pigmentary retinopathies. "Patient IRD-48 was clinically diagnosed with cone-rod dystrophy and was found to be homozygous for the variant c.509T>C in the CNNM4 gene." (PMID 41465088, 2025). "Mutations in CNNM4 are the cause of Jalili syndrome (JS), another inherited disease characterized by the association of amelogenesis imperfecta (AI) and cone-rod dystrophy (CRD)." (PMID 30845649, 2019).
amelogenesis imperfecta (8 papers, 2009 to 2025). Amelogenesis imperfecta (AI) represents a group of developmental conditions affecting the structure and clinical appearance of the enamel of all or nearly all the teeth in a more or less equal manner, and which may be associated with morphologic or biochemical changes elsewhere in the body. "Rare mutations in CNNM4 have recently been reported as a cause of autosomal-recessive cone-rod dystrophy with amelogenesis imperfecta." (PMID 20700443, 2010). "Since magnesium is also incorporated in the mineral of dental hard tissues, we hypothesized that magnesium concentrations in defective enamel resulting from mutations in CNNM4 would be abnormal, if a similar deficiency of magnesium transport also accounted for the amelogenesis imperfecta." (PMID 24194943, 2013).
colon cancer (7 papers, 2016 to 2025). "In contrast, the knockdown of CNNM4, a homolog with the highest magnesium export capacity, increased intracellular magnesium levels in cell culture and enhanced mouse colon cancer malignancy." (PMID 40003994, 2025). "For example, CNNM4 has been proposed as a prognostic marker in colon cancer, where its mRNA levels are frequently reduced in metastatic disease." (PMID 40003994, 2025). "IHC analyses of tissues from patients with colon cancer demonstrated an inverse relationship between CNNM4 expression and colon cancer malignancy, thereby supporting the notion that CNNM4 suppresses the progression of cancer malignancy in humans." (PMID 33450887, 2021). "CNNM4 is a member of the cyclin and cystathionine β-synthase (CBS) domain divalent metal cation transport mediator family and promotes tumor progression by regulating Mg2+ efflux; its level is inversely correlated with malignancy in colon cancer." (PMID 35486664, 2022).
Hypomagnesemia (4 papers, 2013 to 2025). An abnormally decreased magnesium concentration in the blood. "CNNM4, for instance, facilitates magnesium extrusion via Na+/Mg2+ exchange and is essential for intestinal magnesium absorption, as evidenced by hypomagnesemia in CNNM4 knockout mice." (PMID 40003994, 2025). "CNNM4-knockout mice showed hypomagnesemia due to the intestinal malabsorption of magnesium, suggesting its role in Mg2+ extrusion to the inner parts of body." (PMID 24339795, 2013). "Mice genetically engineered not to express CNNM4, which localizes to the epithelial membrane facing to the inner parts of body, show hypomagnesemia due to the defect in magnesium absorption." (PMID 24339795, 2013).
liver disease (4 papers, 2022 to 2025). "CNNM4 is overexpressed in liver diseases, includingnon-alcoholic steatohepatitis and acetaminophen-induced liver injury,leading to aberrant levels of Mg2+." (PMID 40862638, 2025). "There are limited examples focusing on post-transcriptionalregulatory elements, such as miRNAs., Herein, wedemonstrate the regulation of CNNM4 by miRNAs, focusing our validationstudies on miRNAs known to be dysregulated in hepatic disease." (PMID 40862638, 2025). "Work from our and the Martinez-Chantarlaboratories have demonstrated that dysregulation of CNNM4 expressionin various models of liver disease, including NASH and AILI, resultsin changes in cellular levels of free Mg2+." (PMID 40862638, 2025). "Then, hepatic Cnnm4 silencing appeared to be required for amelioration of Mg2+ disturbances in liver disease due to its efflux activity." (PMID 36433951, 2022).
breast carcinoma (3 papers, 2017 to 2025). "Significantly, our results are consistent with a very recentreport that showed CNNM4 being a target for downregulationby miR-24-2-5p in breast cancer cells, with implications in earlystages of bone metastasis." (PMID 40862638, 2025). "We also discovered that a complex between the proteins can be detected in multiple cell types, including the endogenous TRPM7 and CNNM4 proteins in ZR-75-1 breast cancer cells." (PMID 34928937, 2021). "We also found that when overexpressed, HA-TRPM7 has the capacity to bind native CNNM proteins in other cell lines (Hela, opossum kidney proximal tubule (OK), RPTEC/TERT1, and HAP1) and that endogenous TRPM7 interacts with native CNNM4 in ZR-75-1 breast cancer cells." (PMID 34928937, 2021). "Of note, the diminished expression of putative hub genes such as CDKN2B, CNNM4, LRRC19, and MOGAT2 might be the result of inactivation of genes through DNA methylation as their methylation was identified in colorectal, gastric, and breast cancers as well as in leukaemia." (PMID 29088818, 2017).
pancreatic adenocarcinoma (3 papers, 2021 to 2025). "The high expression of CNNM4 is also correlated with high expression of TRPM7 and MAGT1, another magnesium transporter, and this TRPM7/MAGT1/CNNM4 signature is associated with low patient survival in pancreatic adenocarcinoma." (PMID 41395111, 2025). "Further survival analysis conducted showed that higher CNNM4 expression was strongly associated with reduced OS, similarly observed in cases of pancreatic adenocarcinoma." (PMID 39691602, 2024). "High CNNM4 mRNA expression correlates with reduced overall survival in patients with pancreatic adenocarcinoma." (PMID 39691602, 2024). "In pancreatic adenocarcinoma (PAAD), colon adenocarcinoma (COAD) and rectum adenocarcinoma (READ), MAGT1 and CNNM4 mRNA relative levels were increased when compared to their normal corresponding samples (p < 0.01)." (PMID 33450887, 2021).
colon adenocarcinoma (2 papers, 2021 to 2025). "The magnesium efflux function of CNNM4 has tumor-suppressive properties, and CNNM4 knockout enhanced malignant progression in a spontaneous colon adenocarcinoma mouse model (ApcΔ14/+)." (PMID 40003994, 2025).
colorectal cancer (2 papers, 2024 to 2025). A primary or metastatic malignant neoplasm that affects the colon or rectum. "The downregulation of CNNM4 has been detected by IHC in colorectal cancer tissues, showing an inverse correlation with malignancy grade of tumors." (PMID 39691602, 2024). "Moreover, they showed an overexpression of PRL3 and a downregulation of CNNM4 in colorectal cancers suggesting that CNNM4 prevents tumor progression by controlling low Mg2+ intracellular levels and by regulating energy metabolism." (PMID 41395111, 2025).
intestinal polyp (2 papers, 2019 to 2022). Discrete abnormal tissue masses that protrude into the lumen of the intestine. "Recent findings show that suppression of CNNM4 in mice promotes malignant progression of intestinal polyps and is linked to infertility." (PMID 31842432, 2019). "Similar to PRL overexpression, CNNM4 knockdown in cultured cancer cells promotes tumor formation in mice, and Cnnm4 disruption in mice heterogeneously deficient in Apc, which are predisposed to have benign intestinal polyps, stimulates malignant progression of the polyps to invasive adenocarcinomas." (PMID 36336348, 2022).
bipolar disorder (1 paper, 2025). A disorder of the brain that causes unusual shifts in mood, energy, activity levels and the ability to carry out day-to-day tasks. "In addition, CNNM4 and SF3B1 also belong to the bipolar disorder GWAS catalog, reinforcing the confidence level of MAAT’s results." (PMID 39905509, 2025).
male infertility (1 paper, 2022). The inability of the male to effect fertilization of an ovum after a specified period of unprotected intercourse. "CNNM genes have been highly conserved throughout evolution, and the presence of CNNM4 protein was confirmed in human sperm, suggesting that mutations in human CNNM4 may be involved in male infertility." (PMID 35409285, 2022).
nonalcoholic steatohepatitis (1 paper, 2021). "More recently, up-regulation of CNNM4 has been shown to contribute to the development of nonalcoholic steatohepatitis (NASH)." (PMID 34928937, 2021).
Obesity (1 paper, 2024). Accumulation of substantial excess body fat. "In obesity, downregulation of CNNM4 expression inhibits Mg secretion from thermogenic adipocytes, which leads to decreased M2 macrophage polarization and thermogenesis." (PMID 39517124, 2024). "Under obese conditions, lower CNNM4 expression accounted for the decreased Mg secretion which impaired M2 macrophage polarization‐induced thermogenesis and deteriorated the progress of obesity." (PMID 39517124, 2024). "As a result, CNNM4 overexpression in adipocytes or Mg supplementation in adipose tissue ameliorates obesity by promoting thermogenesis." (PMID 39517124, 2024). "Importantly, overexpression of CNNM4 or supplementation of Mg in scWAT promotes thermogenesis and ameliorates obesity." (PMID 39517124, 2024). "Importantly, this mechanism promoted adipose thermogenesis and impaired Mg secretion by CNNM4 downregulation contributed to the progress of obesity." (PMID 39517124, 2024). "Under obese conditions, lower CNNM4 expression accounts for the decreased Mg secretion and obesity." (PMID 39517124, 2024). "Whether CNNM4‐mediated M2 macrophage polarization plays a role in the development of obesity is an interesting topic that requires to be clarified." (PMID 39517124, 2024). "In obesity, the downregulation of Cyclin and CBS domain divalent metal cation transport mediator 4 (CNNM4), a transporter mediating Mg efflux, decreased Mg secretion from thermogenic adipocytes and led to decreased M2 macrophage polarization and energy expenditure." (PMID 39517124, 2024). "Thus, means of promoting this feedback loop by either CNNM4 expression, Mg supplement, or AMI could serve as valuable approaches to combat obesity." (PMID 39517124, 2024).
retinal degeneration (1 paper, 2013). Degeneration of the retina. "We found that the retinal layers were normal and no symptom of retinal degeneration was observed in the retina of CNNM4−/− mice." (PMID 24339795, 2013).
Retinal dystrophy (1 paper, 2023). Retinal dystrophy is an abnormality of the retina associated with a hereditary process. "The genetic diagnosis pointed to the presence of autosomal bi–allelic recessive variants in the CNNM4 gene with further confirmation of the presence of a retinal dystrophy." (PMID 37228816, 2023).
tumor (9 papers, 2019 to 2025). "Both single-factor and multi-factor Cox regression models identified age as a risk factor, and a significant association was found between CNNM4 expression, patient age, and tumor grade in survival analysis." (PMID 39691602, 2024). "Recent studies have linked CNNM4 to tumor growth and metastasis, sparking interest in its potential as a target for cancer therapy." (PMID 39691602, 2024). "The potential molecular mechanisms by which CNNM4 affects OV progression were explored through analyses of the association between CNNM4 expression and tumor immune infiltration." (PMID 39691602, 2024). "On the other hand, CNNM3 and CNNM4 are involved in cancer progression by associating with the highly oncogenic phosphatases of the regenerating liver (PRLs) and by promoting intracellular Mg2+ accumulation that favors tumor growth and metastasis." (PMID 31842432, 2019). "The association of CNNM4 with phosphatases of the regenerating liver, PRLs, abrogates its Mg2+-efflux capacity, thus resulting in an increased intracellular Mg2+ concentration that favors tumor growth." (PMID 31842432, 2019). "H-scores revealed significantly higher CNNM4 immunoexpression in tumor tissues, and IHC revealed lower CNNM4 staining in the cytoplasm of paracancerous cells than in tumor cells." (PMID 39691602, 2024). "CNNM4 protein was also found downregulated in an IHC analysis of cancerous colorectal tissues, and inversely correlates with tumor malignancy." (PMID 33450887, 2021). "CNNM4-dependent Mg2+ efflux is apparently able to suppress tumor progression by regulating energy metabolism: Mg2+ is able to bind several biomolecules, with ATP being most probably the utmost important." (PMID 33450887, 2021). "The role of CNNM4 in cancer may be linked to its association with PRL, which promotes Mg2+ accumulation intracellularly, thereby supporting tumor growth and metastasis." (PMID 39691602, 2024). "Additionally, the relationship between CNNM4 expression and well-known immunotherapy-related tumor markers was examined, revealing associations with MSI, NEO, and TMB across groups with varying levels of CNNM4 expression." (PMID 39691602, 2024). "Cellular Mg2+ transporters SLC41A1 and CNNM4 function as Na+/Mg2+ exchangers, suggesting that Na may be reduced in tumor samples since Mg was elevated, and our results confirmed this possibility." (PMID 31643147, 2019). "Thus, CNNM4 is assumed to be critical for tumor development." (PMID 39691602, 2024). "CNNM4 (cyclin and CBS domain divalent metal cation transport mediator 4), a member of the CNNM (Cyclin M) family, binds to PRL (prolactin) to regulate magnesium homeostasis and influence tumor cell proliferation." (PMID 39691602, 2024).
cancer (5 papers, 2021 to 2025). A tumor composed of atypical neoplastic, often pleomorphic cells that invade other tissues. "Importantly, histological analyses of CNNM4-deficient polyps reveal the presence of invading cancer cells." (PMID 33450887, 2021). "Although CNNM4 is implicated in various cancers, its role in OV remains unclear." (PMID 39691602, 2024). "The mutation rates of different MHGs varied widely across cancer tissues, with ANK3 having the highest mutation rate (47%), followed by KEL (18%), TRPM7 (16%), KCNA1 (13%), CNNM2 (9%), CNNM1 (9%), TFAP2B (9%), CNNM4 (9%), XK (7%), and EDN3 (5%)." (PMID 41174507, 2025). "The downregulation of their expression is associated with better prognosis in several cancers, such as XK in ACC, CNNM4 in READ, KEL in CESC, CNNM3 in KIRC, as well as CNNM2 in LGG and KIRC." (PMID 41174507, 2025). "We demonstrated that CNNM4 promotes cancer proliferation and metastasis through multiple biological assays." (PMID 39691602, 2024). "PRL, frequently overexpressed in cancers, acts as a pseudo phosphatase by binding to CNNM4, modulating magnesium homeostasis." (PMID 39691602, 2024). "High CNNM4 expression is observed in various cancers, where it correlates with poor prognosis due to its impact on cellular growth and immune modulation." (PMID 39691602, 2024). "This would hence mean that the role of CNNM4 is different in some cancers and requires further investigation." (PMID 39691602, 2024). "Further detailed studies are required to clarify the role of CNNM4 as an oncogene and the mechanisms through which Mg2+ dysregulation contributes to cancer progression in OV." (PMID 39691602, 2024). "More recently, CNNM3 and CNNM4 were found to be regulated by PRL phosphatases to increase cellular Mg2+ levels to stimulate cancer cell growth." (PMID 34928937, 2021). "Though there are different points of view, many researchers have indicated that CNNM4 may serve as a predictive marker for cancers." (PMID 39691602, 2024).
CNNM4 also shares sentences with these, for which no sentence is quoted: autosomal recessive cone rod dystrophy (2 papers); -alcoholic steatohepatitis (1); Alström syndrome (1); Bardet-Biedl syndrome (1); breast tumour (1); colon (1); dental disorder (1); hepatocellular carcinoma (1); Infertility (1); Intellectual disability (1); leukaemia (1); liver failure (1); ovarian carcinoma (1); Seizure (1); steatosis (1); Usher syndrome (1).